MMP3 (matrix metallopeptidase 3)
Diseases named in the same sentence as MMP3 in open-access papers (continued):
Sharing a sentence is not in itself a finding about the gene and the disease.
Aortic dissection (3 papers, 2009 to 2022). Aortic dissection refers to a tear in the intimal layer of the aorta causing a separation between the intima and the medial layers of the aorta. "We found three easily measurable parameters (striae atrophicae, TGF-β serum level, MMP-3) that may help to predict the risk of aortic dissection in MFS." (PMID 24720641, 2014). "There were significantly higher levels of MMP-3 in patients with acute myocardial ischemia as compared to acute aortic dissection (17.33 ± 2.03 ng/ml versus 12.92 ± 1.01 ng/ml, p < 0.05)." (PMID 19886986, 2009). "As far as MMP-3 is concerned, it was found that the MMP-3 levels in patients with acute myocardial ischemia were significantly higher than those found in patients with acute aortic dissection." (PMID 19886986, 2009). "Furthermore, blood serum levels of MMP-3 in patients with acute aortic dissection were significantly lower compared to those found in patients with acute myocardial ischemia (12.92 ± 1.10 versus 17.33 ± 2.03 ng/ml, p < 0.05)." (PMID 19886986, 2009). "It has been reported that when aortic dissection occurs, the serum levels of MMP1, MMP2, MMP3, MMP8, and MMP13 are increased, and the expression of MMP9 in the cytoplasm of smooth muscle cells in the aortic wall is enhanced." (PMID 35463768, 2022). "It should be stated, that sample collection happened 7.1 ± 5.1 years after the event of aortic dissection, thus it can be ruled out that the mentioned molecular alterations (elevated TGF-β levels, up-regulated MMP-3) is caused by the dissection itself." (PMID 24720641, 2014). "Among patients with aortic dissection, TGF-β serum level was elevated (43.78 ± 6.51 vs. 31.64 ± 4.99 ng/l, p < 0.0001), MMP-3 was up-regulated (Ln2α = 1.87, p = 0.062) and striae atrophicae were more common (92% vs. 41% p = 0.027) compared to the annuloaortic ectasia group." (PMID 24720641, 2014).
basal cell carcinoma (3 papers, 2022 to 2026). A carcinoma involving the basal cells. "In Basal cell carcinoma, the significant expression of MMP-3 and MMP-14 suggests involvement in local proliferation and stromal remodeling rather than high metastatic capacity." (PMID 42158425, 2026). "In situ, CD200 underwent ectodomain shedding by metalloproteinases MMP3 and MMP11, which released biologically active soluble CD200 into the basal cell carcinoma microenvironment." (PMID 36074574, 2022). "MMP3 and MMP11 have previously been shown to be involved in CD200 ectodomain shedding in basal cell carcinoma and thus may be involved in regulating the cleavage of CD200 in PDAC." (PMID 38619621, 2024).
brain injury (3 papers, 2005 to 2021). Acute and chronic (see also brain INJURIES, CHRONIC) injuries to the brain, including the cerebral hemispheres, CEREBELLUM, and brain STEM. "MMP-3 concentrations were elevated in the molecular layer of the dentate after traumatic brain injury." (PMID 16122387, 2005).
cerebrovascular diseases (3 papers, 2013 to 2022). "MMP3 is known to be an inducer of EMT and MMP3 polymorphism contributes to heterogeneity in vascular remodeling, resulting in cerebrovascular diseases." (PMID 35216046, 2022).
chronic obstructive pulmonary disease (3 papers, 2015 to 2019). A chronic and progressive lung disorder characterized by the loss of elasticity of the bronchial tree and the air sacs, destruction of the air sacs wall, thickening of the bronchial wall, and mucous accumulation in the bronchial tree. "Like MMP1 and MMP3, its common polymorphisms have been linked to chronic obstructive pulmonary disease, cardiovascular disease, and some cancers." (PMID 25111588, 2015).
coinfection (3 papers, 2019 to 2022). The simultaneous infection of a host by multiple pathogen species. "QPCR analysis showed that the expression trend of 10 genes between the co-infection and control groups (IL-17C, NFκB, AP1, C/EBPβ, CXCL1, CXCL8, MMP1, MMP3, GM-CSF, and MUC5AC) was consistent with the RNA-seq results." (PMID 31803158, 2019).
colon adenocarcinoma (3 papers, 2013 to 2023). "Several studies have shown that MMP, including MMP3, over-expression correlates with poor prognosis and metastatic evolution in several cancers, including colon adenocarcinomas." (PMID 24023955, 2013). "This may explains why MMP3 expression strongly increased in colon adenocarcinoma and decreased back to a normal level in metastatic samples." (PMID 24023955, 2013). "Compared with tumor adjacent tissues, EEF1A2, PBK and TIMP1 showed significant upregulation in colon adenocarcinoma, while ATP2A3, CDC25C, MMP3 and NAT1 showed significant downregulation." (PMID 37626132, 2023).
Corneal ulceration (3 papers, 2011 to 2022). "Corneal fibroblasts (activated keratocytes) produce MMPs in response to certain stimuli, with collagenase (MMP-1), stromelysin (MMP-3), and gelatinase (MMP-2) enzymes having been shown to be secreted by these cells in response to stimuli associated with corneal ulceration." (PMID 21364906, 2011). "MMP2, MMP3, and MMP9 have been previously reported to be upregulated in inflammatory/fibrotic diseases of the ocular surface, such as corneal ulcer, ocular burn, and corneal neovascularization." (PMID 35943663, 2022). "Corneal ulceration results from the destruction of stromal collagen by MMPs and other proteases, and we have now shown that triptolide inhibits the expression of MMP-1 and MMP-3 induced by poly(I:C) in human corneal fibroblasts." (PMID 21364906, 2011).
coronary artery stenosis (3 papers, 2013 to 2025). "Genetic polymorphism studies showed that the 6A allele of MMP3 was associated with the increased risks of arterial calcification in DM patients in Japan, and was an independent risk factor for coronary artery stenosis in DM patients in Irian." (PMID 38173213, 2025). "Other univariate analyses show that significant coronary stenosis (above 75%) was related to seven polymorphisms: C667T MTHFR, K469E ICAM1, –1607 1G/2G MMP1, –1612 5A/6A MMP3, K167N LOX-1, –675 4G/5G PAI, and IVS7 FVII." (PMID 23274712, 2013).
Dengue virus infection (3 papers, 2020 to 2023). "In addition, MMP3 has been shown to promote cellular antiviral response against Dengue virus infection." (PMID 32922541, 2020). "Notably, the α-IL-17A Ab also suppressed MMP-8, but not MMP-3, suggesting that MMP-3 plays less of a role in severe dengue." (PMID 37939119, 2023).
dental caries (3 papers, 2018 to 2024). The decay of a tooth, in which it becomes softened, discolored, and/or porous. "The aim of the study was to analyse Czech children with primary/permanent dentition polymorphisms in those genes encoding MMP2, MMP3, MMP9, MMP13, MMP16, and MMP20, which had been previously associated with dental caries in other populations." (PMID 32398053, 2020). "Inhibiting MMP3 shows potential for preventing dental caries." (PMID 39411079, 2024).
diabetic nephropathy (3 papers, 2015 to 2024). "In conclusion, this study has shown promising results regarding MMP-3 and GDF-15 as biomarkers for diabetic nephropathy and neuropathy." (PMID 39000435, 2024). "Matrix metalloproteinase 3 (MMP-3) has been identified in the kidneys and is thought to be involved in diabetic nephropathy." (PMID 39000435, 2024). "Thus far, no studies have been reported regarding plasma MMP-3 and diabetic nephropathy in humans or animals." (PMID 25848912, 2015).
diffuse large B-cell lymphoma (3 papers, 2015 to 2022). "However, in hematological malignancies, MMP-3 expression was decreased in diffuse large B-cell lymphoma (DLBC) and acute myeloid leukemia (LAML)." (PMID 36211828, 2022). "Finally, certain lymphoproliferative diseases are also associated with expression of COL6A1, COL18A1, MMP3 and TIMP1, and a subset of patients with diffuse large B cell lymphoma and adverse prognosis show decreased expression of POSTN, SPARC, COL1A1, COL3A1,CSTK, MMP9 and LAMB3." (PMID 33379263, 2020). "Decrease of plasma levels of MMP-3 was also shown in a case report of diffuse large B-cell lymphoma, not otherwise specified (DLBCL, NOS) associated with RA treated with six courses of rituximab plus cyclophosphamide, doxorubicin, vincristine and prednisone therapy." (PMID 25190551, 2015).
encephalitis (3 papers, 2019 to 2025). An acute inflammatory process affecting the brain parenchyma. "Especially MMP9, MMP8 and MMP3 are vividly upregulated intrathecally in murine encephalitis models, with a potential redundancy of their proteolytic effects." (PMID 40003967, 2025). "Serum levels of MMP-9 were significantly increased in encephalitis, meningitis, and Ramsay Hunt syndrome patients whereas serum MMP-3 levels were higher in meningitis and Ramsay Hunt syndrome compared to controls." (PMID 30777092, 2019). "The patients with encephalitis had the most significantly increased levels of MMPs in CSF, and MMP-3, MMP-8, and MMP-12 were exclusively increased in this group, whereas MMP-9 in CSF was increased in the patients with VZV meningitis." (PMID 30777092, 2019). "In addition, patients with encephalitis showed pronounced increased levels of MMP-3, MMP-8, and MMP 12 in their CSF compared to controls, indicating an association to the severity of this manifestation." (PMID 30777092, 2019). "In addition, patients with encephalitis had pronounced increased levels of MMP-3, MMP-8, and MMP-12 in their CSF compared to controls, suggesting an association to the severity of this manifestation." (PMID 30777092, 2019). "Interestingly, MMP-3 was similarly elevated in the brain during encephalitis induced by West Nile virus supporting its role in encephalitis." (PMID 30759813, 2019). "Encephalitis and meningitis patients differed with respect to other chemokines (CXCL11) and MMPs (MMP-3, MMP-8, MMP-9, and MMP-12), indicating that different location of the virus gives rise to qualitative differences in the ensuing inflammatory response." (PMID 30777092, 2019).
endothelial dysfunction (3 papers, 2015 to 2026). In vascular diseases, endothelial dysfunction is a systemic pathological state of the endothelium (the inner lining of blood vessels) and can be broadly defined as an imbalance between vasodilating and vasoconstricting substances produced by (or acting on) the endothelium. "Tryptase activates metalloproteinases (MMP), such as MMP-1, MMP-2 and MMP-3 and procollagenase, and promotes the degradation of lipoproteins and fibronectin, acting as powerful inflammatory stimulus at the endothelial dysfunction." (PMID 26038676, 2015).
fibromyalgia (3 papers, 2022 to 2026). A chronic disorder of unknown etiology characterized by pain, stiffness, and tenderness in the muscles of neck, shoulders, back, hips, arms, and legs. "Most SNP effect estimates lie to the right of the midline (OR > 1), supporting that increased MMP-3 is associated with increased fibromyalgia risk." (PMID 40958320, 2025). "Matrix metalloproteinase-3 (MMP-3), a key enzyme involved in inflammation and tissue remodeling, has not been genetically validated for its causal relationship with fibromyalgia." (PMID 40958320, 2025). "IVW analysis showed that per 1 standard deviation increase in MMP-3 level was associated with a 0.098% increase in fibromyalgia risk (odds ratio [OR] = 1.00098, 95% confidence interval = 1.00014–1.00182, P = .0225)." (PMID 40958320, 2025). "This study aims to explore the causal association between MMP-3 and fibromyalgia using Mendelian randomization (MR) methods." (PMID 40958320, 2025). "IVW analysis shows that per 1 standard deviation increase in MMP-3 levels is associated with a 0.098% increase in fibromyalgia risk (OR = 1.00098, 95% CI = 1.00014–1.00182, P = .0225)." (PMID 40958320, 2025). "Genetic association between MMP-3 and fibromyalgia: the horizontal axis is the effect of SNPs on MMP-3, and the vertical axis is the effect of SNPs on fibromyalgia." (PMID 40958320, 2025). "This study reveals a potential causal association between MMP-3 levels and fibromyalgia." (PMID 40958320, 2025). "If the causal association between MMP-3 and fibromyalgia is validated in larger samples, it could guide early intervention strategies in high-risk populations." (PMID 40958320, 2025). "Longitudinal GWAS or dynamic MR analyses are needed to clarify whether MMP-3 levels in midlife or adolescence correlate with fibromyalgia risk." (PMID 40958320, 2025). "The IVW analysis showed a positive correlation between MMP-3 levels and fibromyalgia (OR = 1.00098, 95% CI = 1.00014–1.00182, P = .0225), indicating that an increase in MMP-3 may increase the risk of fibromyalgia." (PMID 40958320, 2025). "First, MMP-3 may serve as a biomarker for fibromyalgia risk assessment or treatment monitoring." (PMID 40958320, 2025). "Four MR analysis methods all suggested a positive correlation trend between MMP-3 levels and fibromyalgia." (PMID 40958320, 2025). "Genome-wide association study (GWAS) data for MMP-3 levels (n = 21,758) were obtained from the IEU Open GWAS database, and GWAS data for fibromyalgia were extracted from public databases (n = 361,194)." (PMID 40958320, 2025). "This study uses genetic variations (SNP) as IVs to reduce reverse causality and confounding bias, providing the first genetic evidence for the potential role of MMP-3 in the pathogenesis of fibromyalgia." (PMID 40958320, 2025). "Although sensitivity analyses ruled out a significant horizontal pleiotropy, mechanistic studies are still needed to validate whether MMP-3 is involved in fibromyalgia pathogenesis under different environmental exposures." (PMID 40958320, 2025). "This study supports a potential causal association between MMP-3 and fibromyalgia through genetic evidence, suggesting that MMP-3 may be involved in the pathogenesis of fibromyalgia." (PMID 40958320, 2025). "Also, a correlation between MMP-3 and IL-6 was proposed in fibromyalgia, a common chronic pain, which represents either inflammatory cytokine-induced MMP-3 release or MMP-3 stimulation of local inflammatory cytokine production." (PMID 36684250, 2022). "Moreover, the effects of acute MMP-3 elevation (such as during infection) may differ from those of chronic elevation on fibromyalgia." (PMID 40958320, 2025). "Additionally, the association between MMP-3 and fibromyalgia may be nonlinear (such as a threshold effect), where both extremely low and high MMP-3 levels may increase the risk." (PMID 40958320, 2025).
fibromyalgia (continued). "This study used cross-sectional MMP-3 GWAS data, precluding inference of the temporal sequence between MMP-3 elevation and fibromyalgia onset." (PMID 40958320, 2025). "Based on 2-sample MR analysis, genetically predicted MMP-3 levels are positively correlated with fibromyalgia, supporting that MMP-3 may be involved in the pathogenesis of fibromyalgia." (PMID 40958320, 2025).
fibrosarcoma (3 papers, 2017 to 2024). A malignant mesenchymal fibroblastic neoplasm affecting the soft tissue and bone. "Specifically, it inhibits MMP-1, MMP-3, MMP-7, MMP-9, and MMP-14, which hinders the expansion of HUVECs and the activated process of proMMP-2 regulated by MMP-14 in human fibrosarcoma cells." (PMID 38611849, 2024). "Previous studies have also shown suppression of MMPs in response to IFN-γ, such as MMP-9, which like MMP-1 and MMP-3, also contains AP-1 sites (two) and putative SBEs58–60, and has been shown to be repressed following IFN-γ treatment in astrocytes, fibrosarcomas, and monocytes." (PMID 28819304, 2017).
glomerulosclerosis (3 papers, 2011 to 2020). A hardening of the kidney glomerulus caused by scarring of the blood vessels. "The association of MMPs including MMP-3 and -13 with chemotherapy-induced cell toxicities, such as mucositis, glomerulosclerosis, and neurotoxicity was implicated." (PMID 32963742, 2020).
gouty arthritis (3 papers, 2022 to 2025). "Matrix Metalloproteinase-3 (MMP-3) has been studied in relation to the development of gouty arthritis from HUA." (PMID 39968300, 2025). "Dapansutrile may reduce the expression of MMP3 by regulating IL6, IL18, and IL17A, thereby degrading the extracellular matrix to deal with gouty arthritis." (PMID 36105284, 2022). "Dapansutrile may regulate extracellular matrix degradation by reducing MMP3 expression through IL6, IL18, and IL17A in the treatment of gouty arthritis." (PMID 36105284, 2022). "Finally, dapansutrile may reduce the expression of MMP3 by regulating IL6, IL18, and IL17A, thereby degrading the extracellular matrix to treat gouty arthritis." (PMID 36105284, 2022). "Therefore, Dapansutrile may decrease the expression of MMP3 by regulating IL6, IL18, and IL17A, thereby degrading the extracellular matrix for the treatment of gouty arthritis." (PMID 36105284, 2022).
Granuloma (3 papers, 2013 to 2026). A compact, organized collection of mature mononuclear phagocytes, which may be but is not necessarily accompanied by accessory features such as necrosis. "IL‐17 was expressed in the lymphocytes associated with TB granulomas and MMP‐3 was expressed in the epithelial cells around these TB granulomas." (PMID 29210073, 2018). "MMP3, CCL20 and CCL22 showed significance increase in tuberculoid as compared to the lepromatous lesions adding support to the increased lymphocytes seen in BT granulomas." (PMID 23936569, 2013).
HCMV infection (3 papers, 2015 to 2022). "In particular, HCMV infection led mainly to the over-expression of CCL2, CCL3, CCL11, CXCR4, IL-1β, IL13, MMP1, MMP3, MMP9 and MMP13, SERPINA1, TNFα, and BMP7, and the gradual and constant downregulation of IL13RA2 (up to almost 800-fold at 14 days p.i.)." (PMID 32899126, 2020). "We also found an increase in the secretion of MMP3 and MMP9 at 9 days post HCMV infection that we propose would aid the virus in tissue dissemination from infected pericytes as it traffics through the inner retinal barrier." (PMID 25573478, 2015).
hyperlipidemia (3 papers, 2017 to 2021). "A recent study conducted in IVDs of an ApoE knockout mice model also suggested that hyperlipidemia can increase the expression of MMP3 and accelerate IVDD43." (PMID 28785062, 2017).
juvenile idiopathic arthritis (3 papers, 2006 to 2023). Juvenile idiopathic arthritis (JIA) is the term used to describe a group of inflammatory articular disorders of unknown cause that begin before the age of 16 and last over 6 weeks. "In the aqueous humor of juvenile idiopathic arthritis patients with anterior uveitis, the levels of MMPs (MMP1, MMP3, MMP9) are significantly higher than those in controls." (PMID 35274006, 2022).
laryngeal carcinoma (3 papers, 2013 to 2020). Carcinoma that arises from the laryngeal epithelium. "In this study, we analyzed the gene expression data of 109 laryngeal cancer samples and screened to obtain three important targets (MMP1, MMP3, and MMP10)." (PMID 32636440, 2020). "The green module was mapped on the HQ PPI network, and finally, the potential critical targets MMP1, MMP3, and MMP10 for the treatment of laryngeal cancer were obtained." (PMID 32636440, 2020).
leukemia (3 papers, 2022 to 2025). A malignant (clonal) hematologic disorder, involving hematopoietic stem cells and characterized by the presence of primitive or atypical myeloid or lymphoid cells in the bone marrow and the blood. "When MSCs were co-cultured with Nrf2 overexpressed leukemia RS4; 11 cells, B-ALL mice showed the increased Ki67+/MMP3 ratio." (PMID 39081954, 2024). "In this context, it has been reported that thymoquinone consumption moderated the levels of IL-6 and subsequently suppressed MMP-1, MMP-3, VEGF, and decreased TIMP-1 in Leukemia." (PMID 36518397, 2022). "For MMP-3, there is no data available relating to leukemia, despite its described role in modulating tumor metastasis and progression in several types of cancer." (PMID 40427122, 2025).
lumbar disc degeneration (3 papers, 2012 to 2019). "A polymorphism in the promoter of MMP-1, MMP-2, MMP-3, and MMP-9 genes, which enhance promoter activity, is associated with a higher prevalence of lumbar disc degeneration in Japanese elderly patients and Chinese adult cohorts." (PMID 22394620, 2012).